TNF (tumor necrosis factor)
Diseases named in the same sentence as TNF in open-access papers (continued):
Sharing a sentence is not in itself a finding about the gene and the disease.
psoriasis (continued). "Since biologics that target T cells and TNF-α show clinical benefit in psoriasis, we addressed the involvement of IFN-γ and TNF-α in the pathogenesis of the disease." (PMID 18648529, 2008). "Successful treatment of moderate to severe psoriasis with TNF antagonists improves physical function, as well as social and psychological aspects of psoriasis." (PMID 18831744, 2008). "TNF-α is a cytokine involved in the majority ofinflammatory processes, and its increased activity is found in many skindiseases including psoriasis, SLE, or systemic sclerosis." (PMID 18584045, 2008). "Adalimumab is a fully human monoclonal antibody that blocks tumor necrosis factor, a pro-inflammatory cytokine, and is effective and well-tolerated for patients with moderate to severe psoriasis." (PMID 18831744, 2008). "We report a self-limited nodal-based clinically benign proliferation of T-cells developing in a patient with psoriasis treated concurrently with the TNFα inhibitor etanercept and the anti-CD11a antibody efalizumab." (PMID 18366773, 2008). "Up-regulation of TNF-α and elevation of the TNF-α–inducible gene signature in lesional skin underscore the importance of this cytokine in psoriasis; these data describe a molecular basis for the therapeutic activity of anti–TNF-α agents." (PMID 18648529, 2008). "To mimic an inflammatory milieu as found in psoriasis, we stimulated normal human keratinocytes with a mixture of interferon-γ, TNF-α and IL-1α (pro-inflammatory cytokines; further referred to as Th1 cytokine mix)." (PMID 18523683, 2008). "Adalimumab, a fully human monoclonal antibody that blocks TNF, is effective and well-tolerated for patients with moderate to severe psoriasis." (PMID 18831744, 2008). "In psoriasis, the cytokine expression profile is selectively skewed toward a T1 (i.e., IL-2, TNF-α, IL-12, IFN-γ) and away from a T2 (i.e., IL-2, IL-5, IL-6, IL-10, IL-13) pattern." (PMID 20040934, 2008). "The exact etiology of psoriasis is still unclear but the increased levels and activity of proinflammatory cytokines, such as tumor necrosis factor (TNF)-α were suggested in the development of psoriasis." (PMID 18852869, 2008). "Overall psoriasis rates were over four times higher in patients treated with TNF-α inhibitors compared with patients treated with other disease modifying antirheumatic drugs." (PMID 18727822, 2008). "Recently, we identified a population of CD11c+ myeloid dendritic cells in psoriasis that produce TNF and iNOS, termed "Tip-DCs"." (PMID 17324275, 2007). "Anti-TNFα therapy demonstrates overall various levels of success in arthritis, psoriasis, inflammatory bowel disease and some other inflammatory disorders." (PMID 17034639, 2006). "Compelling evidences indicate that the production of TNF-α plays a central role in psoriasis by sustaining the inflammatory process in the skin as well as in the joints." (PMID 17022813, 2006). "Studies using infliximab, an anti-TNF anti-body, also have shown efficacy in the treatment of psoriasis." (PMID 16756666, 2006). "Other events with a possible relation to TNF-α-blocking therapy included vasculitis, psoriasis, drug-induced systemic lupus erythematosus, dermatomyositis, and a lymphomatoid-papulosis-like eruption." (PMID 15899052, 2005). "Chronic systemic inflammation in psoriasis promotes keratinocyte hyperproliferation through the activation of Th1, Th17, and Th22 lymphocytes and increased production of pro-inflammatory cytokines, such as IL-1, IL-6, IL-12, IL-23 and TNF-α." (PMID 41596291, 2026). "Psoriasis and psoriatic arthritis (PsA) are chronic, immune-mediated inflammatory diseases driven predominantly by dysregulation of the IL-23/Th17 axis, with central contributions from IL-23, IL-17A/F, and TNF-α." (PMID 41596733, 2026). "Biologics used in psoriasis predominantly target TNFα, IL-17, 23, while in AD inhibit IL-4,13,31." (PMID 41481132, 2026).
psoriasis (continued). "According to a study using data from BIOBADADERM, a multicenter, prospective cohort study comparing the risk of infection during the use of biological drugs (from the anti-TNF group and ustekinumab) to classic drugs used in psoriasis, it was significantly increased for TNF antagonists." (PMID 41481132, 2026). "TNFα inhibitor-associated psoriatic alopecia (TiAPA) is an infrequent complication of treatment with infliximab and adalimumab in particular, and surprisingly is more common in subjects with IBD than those treated for psoriasis or PsA." (PMID 41481132, 2026). "Although biologics have markedly improved psoriasis symptoms, they may occasionally trigger paradoxical inflammatory reactions, particularly with IL-17A or TNF-α inhibitors." (PMID 42079624, 2026). "Under inflammatory conditions, TNFα is produced by various cells, both of the immune system (such as macrophages, Th1, Th17, Th22 lymphocytes) and by keratinocytes, and its serum levels correlate with psoriasis severity." (PMID 41481132, 2026). "Currently available biologic drugs for the treatment of psoriasis target TNFα, IL-17, and IL-23." (PMID 41481132, 2026). "Upon exposure to psoriasis-related autoantigens or environmental triggers (e.g., infection or trauma), these IL-17-producing cells release pro-inflammatory cytokines such as IL-17A/F, TNF, IL-26, and IL-29." (PMID 41226338, 2025). "CTLs secrete IL-2, IFN-γ, TNF-α, IL-17, and IL-22, which contribute to psoriasis development." (PMID 40906403, 2025). "The principal receptors of psoriasis treatment are NF-κB, TNF-α, and interleukin IL-6." (PMID 38712377, 2025). "The therapeutic efficacy of IL-17 inhibitors in psoriatic arthritis, regardless of prior TNF inhibitor exposure, may contribute to the comparability between the drug retention of IL-17 inhibitors used for psoriasis aggravation and that of TNF inhibitors." (PMID 40615873, 2025). "Aberrant T cell-mediated responses and cytokine release (e.g., IL-17, IFN-γ, TNF-α) drive keratinocyte hyperproliferation and differentiation abnormalities while also affecting cardiovascular and metabolic systems, underscoring psoriasis as a systemic immune-mediated disorder." (PMID 41471291, 2025). "This might be due to the role of pro‐inflammatory cytokines (i.e. TNF‐α, IL‐6, IL‐23 and IL‐17) that can be found in the onset and pathogenesis of both AP and Psoriasis." (PMID 40105908, 2025). "Proinflammatory cytokines, IL-6 and TNF-α, which are elevated in patients with psoriasis, are also involved in the stimulation of prothrombotic factors that may result in thrombosis." (PMID 40584532, 2025). "Although TNF inhibitors are commonly used to treat psoriasis, paradoxical skin reactions can rarely occur and may even trigger new-onset psoriasis." (PMID 40109802, 2025). "Additionally, HS patients have been found to have higher systemic inflammatory markers (C-reactive protein, circulating leukocyte counts) and pro-inflammatory cytokine levels (TNF-α) than other chronic inflammatory diseases like psoriasis." (PMID 40004643, 2025). "In addition to uveitis, TNF-alpha inhibition can also induce other autoimmune diseases such as demyelination, sarcoidosis, vasculitis, vitiligo, alopecia areata, psoriasis and thyroiditis as well as VKH syndrome-like disease (VKHLD)." (PMID 41142785, 2025). "Furthermore, the authors highlighted TNF-α as a more reliable biomarker than other cytokines for monitoring psoriasis severity during follow-up." (PMID 40310305, 2025). "TNF inhibitors (TNFi) have a well-established efficacy and safety profile, making them a reliable option for psoriasis and psoriatic arthritis; however, they carry risks such as tuberculosis reactivation, loss of efficacy due to anti-drug antibodies, and potential paradoxical psoriasis." (PMID 40092026, 2025). "Targeting the interactions between IL-22R1 and cytokines such as IL-20, IL-24, IL-17, TNF, and IL-1β could improve clinical outcomes in psoriasis treatment." (PMID 40303401, 2025).
psoriasis (continued). "The combination of TNF‐α and IL‐17A has a pivotal role in the inflammatory cascade of psoriatic keratinocytes, where they activate the NF‐κB signaling pathway, leading to the overexpression of downstream genes, including Arg1 and psoriasis‐related genes." (PMID 39665264, 2025). "This could be related to the inflammatory activity of adipose tissue, which secretes pro-inflammatory cytokines such as TNF, IL-1, and IL-6, which could further exacerbate systemic inflammation that overlaps with psoriasis." (PMID 39775226, 2025). "Therefore, we designated TNF-α (50 ng/mL) as the inducer of a psoriasis-like state in keratinocytes." (PMID 40507893, 2025). "Finally, the expression of TNF-α was shown to be decreased by about seven times in the psoriasis mouse model." (PMID 40299379, 2025). "Additionally, both TNF‐α and IL‐17 signaling pathways are crucial in the inflammatory processes of psoriasis, leading to hyperinflammation in keratinocytes and attracting additional immune cells to the skin." (PMID 39665264, 2025). "In addition, IL-36G upregulates the expression of CCN1 and S100A7A, leading to the production of excessive pro-inflammatory factors by the cells, including IL-1, IL-6, IL-8, IL-36, and TNF, which promotes psoriasis." (PMID 40735322, 2025). "Notably, eczema is a common adverse effect of anti-TNF-α therapy that has been reported in up to 20% of patients receiving long-term treatment for psoriasis, arthritis, or inflammatory bowel disease." (PMID 40312358, 2025). "Building on this finding, by modeling the internal environment of psoriasis, we hypothesize that TNF-α-treated HaCaTs-derived exosomes can deliver AGAP2-AS1 to CD4+ T cells, potentially promoting CD4+ T cell differentiation towards Th1 and Th17 phenotypes." (PMID 40520230, 2025). "For patients requiring systemic therapies, biological medications such as TNF-alpha inhibitors (Adalimumab, Etanercept, Infliximab), IL-12/IL-23 inhibitors (Ustekinumab), and IL-17 inhibitors (Secukinumab and Ixekizumab) are available for psoriasis treatment." (PMID 40310305, 2025). "Accordingly, the results of numerous genome-wide association studies (GWAS) and clinical trials support the central role of the inflammatory signaling molecular pathways of TNF-α, IL-23, and IL-17 as the “founding fathers” of the pathogenesis of psoriasis, particularly plaque psoriasis." (PMID 41464777, 2025). "Shared inflammatory pathways, including elevated IL-6, TNF-α, and IL-17, may link psoriasis with psychiatric disorders such as depression and anxiety." (PMID 40428224, 2025). "Moreover, treatment with a cocktail of cytokines (IL-17A, IFNγ, TNFα) to induce a psoriasis-like phenotype in keratinocytes, increased ALOX15B RNA and protein expression." (PMID 39843435, 2025). "Although biologics and immunosuppressants (TNF-α inhibitors, dupilumab, etc.)may be required for AD and/or psoriasis with significant severity, their long-term fetal safety is not well understood, and more investigation is needed for this population." (PMID 40310306, 2025). "We observed that TNF-α-treated HaCaTs-derived exosomes can accelerate the psoriasis process by delivering AGAP2-AS1 to promote CD4+ T cell differentiation towards Th1 and Th17 cells and secretion of more inflammatory factors such as IFN-γ and IL-17A, which affect the immune microenvironment." (PMID 40520230, 2025). "Recent research suggests that estrogen affects the expression of immune cells (DCs and γδT cells), chemokines (CCL5 and CXCL10), and cytokines (TNF-α, IL-23, and IL-17 family), which worsens cutaneous inflammation in psoriasis and provides new insights for developing treatment strategies." (PMID 40303401, 2025). "Furthermore, the amino acid levels in psoriasis patients respond to Etanercept (a biologic anti-TNFα drug), with their concentrations decreasing during therapy to levels similar to those seen in healthy individuals." (PMID 39982364, 2025).
psoriasis (continued). "TNF-α inhibitors may help patients with NAFLD with their psoriasis, but more extensive cohort studies are needed to validate this conclusion." (PMID 40278401, 2025). "Additionally, miR-125b also regulates inflammatory cytokines such as STAT3 and TNF-α, crucial to the inflammatory cascade in psoriasis." (PMID 39997616, 2025). "SNPs in TLR2, TNF, SLC12A8, ZNF816A and TNFAIP3 genes were associated with 3-month response (measured as PASI90 and absolute PASI < 1) to Secukinumab and Ixekinumab in 19 psoriasis patients." (PMID 41153404, 2025). "Therapies effective for psoriasis/PsA, such as TNF and IL-17 inhibitors, may exacerbate inflammatory myopathies, while JAK inhibitors and corticosteroids appear more effective in managing overlap cases." (PMID 40861474, 2025). "Psoriasis is a chronic inflammatory condition characterized by systemic inflammation, with elevated levels of proinflammatory cytokines, including interleukin-1β, interleukin-6, and tumor necrosis factor α." (PMID 40861447, 2025). "The reduced levels of omentin in psoriasis patients may suggest heightened TNF-α-related inflammation, contributing to the inflammatory processes involved in psoriasis pathogenesis." (PMID 40343299, 2025). "For example, in the imiquimod (IMQ)-induced psoriasis model, enhanced features of psoriatic inflammation are associated not only with increased expression of STAT3, NF-kB, IFN-γ and TNF-α in CD4+ T cells but also activation of lymphocyte-specific protein tyrosine kinase (Lck)." (PMID 40868162, 2025). "The data suggest that subcutaneous administration of exosomes derived from hUCB-MSCs preconditioned with IL-17, IL-22, and TNF-α has therapeutic potential for treating skin inflammation and could be applied in psoriasis treatment." (PMID 40906403, 2025). "Psoriasis is a chronic immune-mediated skin disorder characterized by aberrant keratinocyte proliferation, immune cell dysregulation, and sustained inflammation driven by cytokines, such as TNF-α, IL-17, and IL-23." (PMID 40690118, 2025). "It has been shown that a mixture of IL-17, IL-22, and TNF-α resulted in destabilization of the epidermis, parakeratosis, and hypogranulosis, resembling partially the lesional psoriasis phenotype, and several 3D models have been proposed to study psoriasis features." (PMID 40243580, 2025). "Treatment of psoriasis has been revolutionized with the introduction of biologics and today several biologics, target specific cytokines in the psoriasis pathogenesis, including drugs targeting tumor necrosis factor alpha (TNF-α), interleukin (IL)-12p40, IL-17, and IL-23p19." (PMID 41009564, 2025). "Therefore, this study systematically evaluates the efficacy and safety of various biologics—specifically IL-17, TNF-α, and IL-23 inhibitors—in patients with erythrodermic psoriasis (EP) by integrating available clinical evidence." (PMID 41235248, 2025). "Blocking the production of TNF α helps to halt the inflammatory cycles of psoriasis." (PMID 40343294, 2025). "Additionally, activated pDCs and macrophages release pro-inflammatory cytokines such as IFN-α and TNF-α, further amplifying the inflammatory cascade in psoriasis pathogenesis." (PMID 41226338, 2025). "Emerging evidence suggests SARS-CoV-2 infection may exacerbate psoriasis, supported by elevated plasma inflammatory cytokines (e.g., granulocyte-colony stimulating factor, tumor necrosis factor-alpha) correlating with disease severity." (PMID 41306982, 2025). "Moreover, other psoriasis-related pathogenic cytokines like IL22 and TNF-α were downregulated in αβT from Lztr1-deficient mice." (PMID 41162356, 2025). "Moreover, specific case reports have documented the emergence of eruptive seborrheic keratoses following the initiation of treatments such as adalimumab, a tumor necrosis factor (TNF) inhibitor commonly used in psoriasis management." (PMID 40141829, 2025). "The pro-inflammatory cytokine IL-9 secretes IFN-γ, TNF-α, IL-17, and IL-13 in psoriasis." (PMID 40690118, 2025).
psoriasis (continued). "However, despite their efficacy, clinicians must remain vigilant for paradoxical reactions, such as the development or worsening of psoriasis, reported in some patients undergoing TNF inhibitor therapy." (PMID 40678000, 2025). "As a main originator of inflammatory signaling, TNF-α triggers a cascade that includes IL-6 and other cytokines, particularly in acute and chronic inflammatory disorders such as inflammatory bowel disease and psoriasis." (PMID 39755644, 2025). "Research suggests that low estrogen levels may increase pro-inflammatory cytokine activity, such as TNF-α and IL-6, which are key players in psoriasis pathogenesis." (PMID 39860587, 2025). "Other research has demonstrated that TNF-α, a key mediator of inflammation in psoriasis, plays a significant role in angiogenesis by promoting the expression of pro-angiogenic factors such as VEGF, contributing to the pathogenesis of angiogenesis in psoriatic skin." (PMID 40282856, 2025). "Moreover, the demographic, clinical outcomes and histological features in patients with paradoxical psoriasis induced by non‐TNF‐α inhibitor biologics are limited, particularly in cases associated with alopecia." (PMID 40944329, 2025). "Additionally, it reacted well to treatments that disrupt three pathways that are effectively addressed in psoriasis: TNFα, IL-12/23p40, and IL-23p19." (PMID 40563994, 2025). "Furthermore, RT-qPCR analysis of pyroptosis-associated inflammatory cytokines revealed significantly increased expression of IL1β, IL6, and TNFα in psoriasis-derived MDMs compared to healthy controls." (PMID 40722833, 2025). "The high incidence of LTBI restricts treatment options for psoriasis, as TNF-alpha inhibitors, unlike IL-17 blockers, are often associated with the risk of latent tuberculosis reactivation." (PMID 40092026, 2025). "Among inflammatory dermatoses, psoriasis exhibits the strongest overlap with dementia genetics, with shared susceptibility loci including APOE, IL12B, and HLA-DRB5, and transcriptional regulators such as ZNF384 that converge on IL-17/TNF signaling." (PMID 41465136, 2025). "T cells, especially T helper (Th1 and Th17) cells, are known for driving pro-inflammatory responses in psoriasis by releasing cytokines such as IL-17, IL-22, and TNF-α, which stimulate keratinocyte hyperproliferation and sustain the characteristic plaques and scaling of psoriatic skin." (PMID 39860587, 2025). "Biologics may also precipitate NV - for example, biopsy-proven NV after one year of etanercept (a TNF-α inhibitor) in a psoriasis patient, improving after withdrawal." (PMID 41267735, 2025). "Tumor necrosis factor (TNF)-α and other inflammatory cytokines are believed to be involved in the relationship between NAFLD and psoriasis, although the precise mechanism underlying this correlation is still unknown." (PMID 40278401, 2025). "These Th cells, in turn, produce a cascade of cytokines, including IL-17, interferon-gamma (IFN-γ), tumor necrosis factor-alpha (TNF-α), and IL-22, which directly stimulate keratinocyte hyper proliferation and contribute to the inflammatory state characteristic of psoriasis." (PMID 40072672, 2025). "Similarly, HS patients have been found to have higher systemic inflammatory markers (C-reactive protein, circulating leukocyte counts) and pro-inflammatory cytokine levels (TNF-α) than other chronic inflammatory diseases like psoriasis." (PMID 40004643, 2025). "The intermediate period (2001–2010) witnessed dramatic thematic expansion to nine distinct research areas, with the original psoriasis theme generating substantial flows into TNF-α research (220 occurrences) and double-blind methodological approaches (168 occurrences)." (PMID 41011289, 2025). "TNF-α, IL-17 and IL-23 constitute the core inflammatory axis in psoriasis." (PMID 40303401, 2025).